APBB3 (amyloid beta precursor protein binding family B member 3)
Description:
May modulate the internalization of amyloid-beta precursor protein.
Synonyms: Fe65L2; SRA
Tractability: PROTAC: ubiquitination databases record sites on it.
Gene: Protein-coding gene on chromosome 5 (140,558,268 to 140,564,781, reverse strand). Ensembl gene ENSG00000113108.
Subcellular location: Cytoplasm; Nucleus; Nucleus (Isoform I-214); Nucleus (Isoform I-245)
Subcellular location (Human Protein Atlas): Actin filaments; Nuclear bodies; Cytosol
Gene Ontology:
Molecular function: low-density lipoprotein particle receptor binding; protein binding; amyloid-beta binding; molecular adaptor activity
Biological process: positive regulation of protein secretion; regulation of DNA-templated transcription
Cellular component: cytosol; membrane; nuclear body; nucleus; cytoplasm
Genetic constraint (gnomAD): Loss-of-function variants: 50 observed, 65.02 expected, observed/expected ratio (o/e) 0.77, 90% interval 0.61 to 0.97. The upper end of that interval is the gene's LOEUF score, 0.97, which puts it in group 4 of 6, group 1 being the genes least tolerant of losing a copy. Missense variants: 550 observed, 669.89 expected, observed/expected ratio (o/e) 0.82, 90% interval 0.76 to 0.88. Synonymous variants: 235 observed, 247 expected, observed/expected ratio (o/e) 0.95, 90% interval 0.86 to 1.06.
Homologues: Orthologues: chimpanzee APBB3 (98% identical), macaque APBB3 (97% identical), dog APBB3 (95% identical), pig APBB3 (94% identical), guinea pig APBB3 (93% identical), mouse Apbb3 (92% identical), rat Apbb3 (91% identical), rabbit APBB3 (82% identical), tropical clawed frog apbb3 (53% identical), zebrafish apbb3 (51% identical), Caenorhabditis elegans feh-1 (27% identical). Paralogues in human: APBB2 (42% identical), APBB1 (38% identical).
Diseases named in the same sentence as APBB3 in open-access papers:
APBB3 is named in the same sentence as 7 diseases in open-access papers, as found by Europe PMC text mining. Sharing a sentence is not in itself a finding about the gene and the disease. The quoted sentences say what the papers report.
cognitive decline (1 paper, 2010). "In our dataset, we observe APBB3 expression being upregulated with the increasing cognitive decline, following the same pattern of LRP10." (PMID 20405009, 2010).
APBB3 also shares sentences with these, for which no sentence is quoted: Alzheimer disease (1 paper); cancer (1); Fanconi anemia (1); metabolic disorders (1); neurological diseases (1); theileriasis (1).